ANOS1 (anosmin 1)
Diseases named in the same sentence as ANOS1 in open-access papers (continued):
Sharing a sentence is not in itself a finding about the gene and the disease.
colorectal cancer (3 papers, 2017 to 2025). A primary or metastatic malignant neoplasm that affects the colon or rectum. "Moroever, it also indicates that ANOS1 gene undergoes continuous activation, leading to the promotion of tumors that cause colorectal cancer." (PMID 28854193, 2017). "The overexpression of ANOS1 is also related to development and metastasis of colorectal cancer and its expression is closely related to the overall survival rate of patients." (PMID 33470396, 2021). "We found that there was a significant difference between the expression level and methylation level of ANOS1 gene in normal tissue and different stages of colorectal cancer (P < 0.0001)." (PMID 28854193, 2017). "Based on these observations, we conclude that ANOS1 plays an extraordinary role in the progression of colorectal cancer." (PMID 28854193, 2017). "In our experiment, the ANOS1 gene showed up-regulated expression levels continuously, whereas the methylation level showed downregulated levels when the colorectal cancer progressed through the four clinical stages of development and metastasis." (PMID 28854193, 2017). "With the progression of colorectal cancer, the expression level of ANOS1 gene continued to increase but the methylation level continued to decrease." (PMID 28854193, 2017). "We determined the expression and methylation levels of ANOS1 gene by compiling the expression profile data and methylation data of patients with colorectal cancer." (PMID 28854193, 2017). "The results indicate that ANOS1 gene shows continous activation when there is progression of colorectal cancer in patients." (PMID 28854193, 2017). "We obtained this information by analyzing the expression profile data and methylation data of ANOS1 gene in colorectal cancer." (PMID 28854193, 2017). "Since both the expression level and methylation level of ANOS1 gene underwent dramatic changes, we infered that ANOS1 gene was in a state of continuous activation during the progression of colorectal cancer." (PMID 28854193, 2017). "This indicates that that the expression level of ANOS1 gene was closely related to the progression of colorectal cancer." (PMID 28854193, 2017). "Because ANOS1 expression is rarely investigated in patients with colorectal cancer, we decided to focus our attention on ANOS1 in this study." (PMID 28854193, 2017). "All these evidences prove that ANOS1 gene is a very important factor that needs to be further investigated in future research studies of colorectal cancer." (PMID 28854193, 2017). "After performing GSEA analysis on the expression profile data of colorectal cancer cases, we divided the results into two classes based on the expression value of ANOS1 gene." (PMID 28854193, 2017). "This phenomenon indicates that ANOS1 gene shows continuous activation during the progression of colorectal cancer." (PMID 28854193, 2017). "Furthermore, the co-expression partners of ANOS1 gene were screened using cBioPortal tool: we analyzed the data of 633 cases of colorectal cancer in TCGA database." (PMID 28854193, 2017). "Finally, we would like to reiterate that ANOS1 gene can be a guiding factor in the clinical treatment of colorectal cancer." (PMID 28854193, 2017). "Furthermore, ANOS1 gene not only meets such requirements, but it is also closely related to the survival time of patients with colorectal cancer." (PMID 28854193, 2017). "Thus, we elucidated the possible molecular mechanism through which ANOS1 instigates the progression of colorectal cancer in patients." (PMID 28854193, 2017). "This indicates that ANOS1 gene played a very important role in colorectal cancer." (PMID 28854193, 2017). "Thus, ANOS1 gene plays an important role in the development of colorectal cancer." (PMID 28854193, 2017). "Moreover, only a handful of studies might have investigated the relationship between colorectal cancer and the expression of ANOS1 gene." (PMID 28854193, 2017).
colorectal cancer (continued). "Thus, ANOS1 and CTHRC1 genes promote the development and metastasis of colorectal cancer." (PMID 28854193, 2017).
hearing loss (3 papers, 2017 to 2025). "Hence, in addition to the typical features of KS, individuals with mutationsin ANOS1 have also been reported with defects such as renalagenesis, cleft palate, mirror movements, and sensorineural hearing loss." (PMID 41165467, 2025). "In a clinical sense, recognizing those IHH genes and associated phenotypes may improve our diagnostic capabilities by enabling us to prioritize the screening of particular gene(s) such as synkinesia (ANOS1), dental agenesis (FGF8/FGFR1) and hearing loss (CHD7)." (PMID 29280744, 2017).
Infertility (3 papers, 2019 to 2023). "The mutations at the SNPs of TEX11 (rs4844247), LHB (rs4146251380), USP26 (rs61741870) and (rs41299088), and ANOS1 (rs2229013) were displayed in only one of eight infertile men." (PMID 37895049, 2023).
Intellectual disability (3 papers, 2015 to 2025). "Compared with patients with a point mutation in ANOS1, patients with complete deletion of ANOS1 may present with other symptoms, such as short stature, chondrodysplasia punctata, intellectual disability, and steroid sulfatase deficiency." (PMID 32670353, 2020).
multiple sclerosis (3 papers, 2014 to 2020). A progressive autoimmune disorder affecting the central nervous system resulting in demyelination. "FGF-2 and Anosmin-1, which are markers for the level of inflammation of multiple sclerosis lesions, participate in oligodendrocyte precursor cell migration via FGF receptor 1 (FGFR1)." (PMID 27642302, 2016). "Anosmin-1 and FGF-2 could possibly be diagnostic markers in multiple sclerosis (MS), because their expression level varies between different types of MS." (PMID 24735639, 2014).
glioblastoma (2 papers, 2014 to 2020). The most malignant astrocytic tumor (WHO grade IV). "As our gene analyses implicated KAL1 in glioblastomas, we decided to investigate the putative tumor-promoting activities of anosmin-1 in vitro using three different glioblastoma cell lines – LN229, A172, and U87MG." (PMID 24189182, 2014). "Anosmin-1 enhanced glioblastoma cell motility and colocalized with the leading edge of migrating cells while enhancing uPA and MMP2/9 activities." (PMID 24189182, 2014). "The tumor-promoting capacity of anosmin-1 was demonstrated in the glioblastoma cell lines, where anosmin-1 enhanced cell motility and proliferation." (PMID 24189182, 2014). "As high-mitotic index is the hallmark of malignant tumors, we sought to assess the effects of anosmin-1 in glioblastoma cell proliferation by two approaches." (PMID 24189182, 2014). "Anosmin-1 significantly increased cell motility by 50% in LN229, 53% in A172, and 30% in U87MG compared with SFM control, indicating considerable effects of anosmin-1 in multiple glioblastoma cell lines." (PMID 24189182, 2014). "We also found that anosmin-1 enhanced proliferation and motility of glioblastoma cells in vitro, formed a complex with integrin β1 inducing downstream signaling, and modulated cell adhesion." (PMID 24189182, 2014). "Therefore, anosmin-1 increases the proteolytic activities of MMP2/9 and uPA in glioblastoma cells, which may contribute to the ECM remodeling during tumor invasion." (PMID 24189182, 2014).
metastatic tumors (2 papers, 2014 to 2025). "Our findings showed significantly higher ANOS1 expression in the lymph node metastatic tumors than primary tumors." (PMID 40546398, 2025).
esophageal cancer (1 paper, 2025). A primary or metastatic malignant neoplasm involving the esophagus. "Moreover, ANOS1 expression was significantly enhanced in esophageal cancer patients and cell lines, and its increased expression was associated with advanced T stage and worse disease-free survival of esophageal cancer patients." (PMID 40529813, 2025).
female infertility (1 paper, 2022). Diminished or absent ability of a female to achieve conception. "In addition, different genetic abnormalities have been reported to cause female infertility, such as chromosomal alterations and single gene mutations [Anosmin 1 (ANOS1), Gonadotropin Releasing Hormone (GnRH) and Homoebox (HOX) genes]." (PMID 35938101, 2022).
lung adenocarcinoma (1 paper, 2021). A carcinoma that arises from the lung and is characterized by the presence of malignant glandular epithelial cells. "However, the diagnostic value of ANOS1 and its regulatory relationship with BMP5 are currently unclear, and there is a large value in future exploration in lung adenocarcinoma." (PMID 34745928, 2021).
prostate carcinoma (1 paper, 2020). A carcinoma that arises from epithelial cells of the prostate gland. "Anosmin-1 also directly interacts with heparan sulfate for the cell surface localization of the anosmin-1–uPA complex that promotes cell proliferation of prostate cancer cells." (PMID 31932617, 2020).
Strabismus (1 paper, 2020). A misalignment of the eyes so that the visual axes deviate from bifoveal fixation. "One out of the 20 cases showed strabismus, but only deletion of STS and ANOS1 was detected." (PMID 32670353, 2020).
X-linked deafness (1 paper, 2024). "First, some X-linked deafness genes were not included in the predefined panel containing 227 HL-related genes, such as RPS6KA3, EFNB1, HDAC8, ARX, and ANOS1, which may cause a negative molecular diagnosis for some patients." (PMID 39272213, 2024).
tumor (15 papers, 2010 to 2026). "A significant association was observed between ANOS1 expression in advanced GC and various clinical pathological characteristics, including tumor infiltration, lymph node status, clinical TNM stage, and vascular invasion." (PMID 40546398, 2025). "Previous studies have demonstrated a strong association between ANOS1 and various malignant tumors, such as colon cancer, lung cancer, and ovarian cancer and its abnormal expression promotes tumor cell growth, metastasis, and poor prognosis." (PMID 40546398, 2025). "Consequently, investigating the relationship between ANOS1 and tumor-associated immune cell infiltration is critically important." (PMID 40546398, 2025). "Collectively, our research demonstrated the significant involvement of ANOS1 in the progression of GC, specifically in relation to tumor invasion and metastasis." (PMID 40546398, 2025). "Our volcano plot and GO analysis showed the significant downregulation of tumor-suppressive genes, such as ANOS1, CDH11, COL4A5, POSTN, PTN, and BEX1 in As- transformed cells, which is considered an early event of carcinogenesis." (PMID 35954277, 2022). "With respect to the different effects observed with human OPCs and other tumor cells, anosmin-1 seems to promote/attract the migration of malOPCs and immortalized cell lines (; data herein)." (PMID 32498223, 2020). "Moroever, ANOS1 gene plays an important role in cell adhesion, cell migration, and molecular events that are closely related to tumor metastasis." (PMID 28854193, 2017). "Combined, these data suggest that anosmin-1 can facilitate tumor cell proliferation, migration, invasion, and survival." (PMID 24189182, 2014). "ShRNA-mediated knockdown of anosmin-1 attenuated motility and growth of tumor cells and induced apoptosis." (PMID 24189182, 2014). "When the shRNA infected cells were examined for motility, all three shRNAs caused a significant decrease, indicating the essential role of anosmin-1 in tumor cell motility." (PMID 24189182, 2014). "In a mouse xenograft model, anosmin-1-expressing tumors grew faster, indicating the role of anosmin-1 in tumor microenvironment in vivo." (PMID 24189182, 2014). "It is conceivable that anosmin-1 concentrates these proteases at the leading edge of the developing tumor, contributing to their infiltration." (PMID 24189182, 2014). "This study explores ANOS1 expression in GC and its mechanism in tumor metabolic reprogramming." (PMID 41749431, 2026). "Mechanistically, knockdown of ANOS1 promotes oxidative phosphorylation via the receptor tyrosine kinase pathway, suppresses glycolysis, and inhibits the proliferative, migratory, and invasive capacities of tumor cells." (PMID 41749431, 2026). "Therefore, we randomly selected 40 patients with the corresponding lymph node metastases from advanced GC and examined the differential expression of ANOS1 in the primary tumor and corresponding metastatic lesions." (PMID 40546398, 2025). "This might contribute to cancer cell dispersion and metastasis, while anosmin-1 can contribute to the immobilization of cells in both physiological conditions (data herein) and in non-tumoral diseases like MS." (PMID 32498223, 2020). "Likewise, the opposing or cooperative effects of FGF2 and anosmin-1 on tumor cells are still to be evaluated." (PMID 32498223, 2020). "Since ANOS1 is located in the extracellular matrix, it may be probably involved in the tumor microenvironment constitution." (PMID 28854193, 2017). "In few reports, it was proved that ANOS1 was related to tumor." (PMID 28854193, 2017). "Anosmin-1 may also enhance the invasion of tumor cells within the ECM by modulating cell adhesion and activating extracellular proteases." (PMID 24189182, 2014). "Moreover, anosmin-1 increased the extracellular protease activities, supporting its role in tumor invasion." (PMID 24189182, 2014).
tumor (continued). "Consequently, ANOS1 may contribute to diminished tumor cell adhesion through the downregulation of E-cadherin, thereby facilitating the EMT process." (PMID 40546398, 2025). "Statistical analysis showed significant tumor-specific upregulation of WFDC1, WFDC2, WFDC3, SLPI, PI3, and ANOS1 (P < 0.0001), while WFIKKN1 was notably downregulated in neoplastic tissues (P < 0.0001)." (PMID 40350979, 2025). "High ANOS1 expression was correlated with tumor infiltration, lymph node metastasis, TNM stage, and vascular invasion in advanced GC, indicating its role in tumor invasiveness and metastasis." (PMID 40546398, 2025). "While FGF2 was a chemoattractant for human and murine OPCs, anosmin-1 only attracted OPCs isolated from tumor samples and repelled those from non-tumoral samples." (PMID 32498223, 2020). "However, the effects of anosmin-1 on OPC migration differed dramatically in function of both species and age, increasing the motility of P0 and tumor-related human OPCs (malOPCs and also the HOG cell line), while it slowed down the migration of P15 and P60/adult OPCs, and that of haOPCs." (PMID 32498223, 2020).
cancer (8 papers, 2012 to 2025). A tumor composed of atypical neoplastic, often pleomorphic cells that invade other tissues. "In order to explore only genes related to cancer, we selected four genes, including three that were upregulated via copy number gain (ANOS1, ETV1, and XPNPEP2) and one gene (PCDH11Y) that was downregulated via copy number loss." (PMID 33470396, 2021). "Nevertheless, it was suggested elsewhere that the Anos1 gene (former Kal-1 gene;) would be a suppressor for other cancer types, which merits more systematic study." (PMID 32498223, 2020). "The analysis revealed that ANOS1 is involved in the ECM receptor interaction, focal adhesion, hematological cell lineage, chemokine signaling pathway, pathways in cancer, and transforming growth factor (TGF)-β signaling pathway." (PMID 40546398, 2025). "ANOS1 was predominantly enriched in pathways related to ECM receptor interaction, focal adhesion, hematological cell lineage, chemotherapy signaling, pathways in cancer, and the TGF-β signaling pathway in GC." (PMID 40546398, 2025). "GSEA analysis revealed significant enrichment of ANOS1 in multiple oncogenic pathways, particularly extracellular matrix (ECM) receptor interactions, focal adhesion, hematopoietic cell lineage, chemokine signaling pathways, pathways in cancer, and transforming growth factor-β signaling pathway." (PMID 40546398, 2025).
gastrointestinal tumors (1 paper, 2021). "At present, the functions of ANOS1 in tumors are mainly concentrated in gastrointestinal tumors." (PMID 34745928, 2021).
ANOS1 also shares sentences with these, for which no sentence is quoted: Anosmia (18 papers); genetic disorder (4); CHARGE syndrome (3); astrocytic tumor (2); breast cancer (2); male infertility (2); oral squamous cell carcinoma (2); ovarian carcinoma (2); 5-alpha-reductase deficiency (1); adenocarcinoma (1); adrenal hyperplasia (1); adrenal hypoplasia congenita (1); androgen insensitivity syndrome (1); astrocytoma (1); cardiovascular disease (1); cervical cancer (1); choanal atresia (1); chondrodysplasia punctata (1); cleft lip (1); cleft palate (1); communication disorder (1); congenital hypopituitarism (1); developmental delay (1); dysplasia (1); endocrine disorders (1); endometrial cancer (1); glioma (1); Hearing impairment (1); hepatocellular carcinoma (1); hyperlipidemia (1).
A further 32 diseases each share a sentence with ANOS1 in 1 paper.